CD34 (CD34 molecule)
Diseases named in the same sentence as CD34 in open-access papers (continued):
Sharing a sentence is not in itself a finding about the gene and the disease.
leukemia (continued). "Having determined that BH3 mimetics induce apoptosis to a greater degree in BP-CML CD34+ population, which contains disease-driving leukemia stem cells, we investigated whether BH3 mimetics are able to decrease the functional colony-forming capacity of BP-CML cells." (PMID 36379918, 2022). "Moreover, BK124.1 induced apoptosis in the rare CD34+/CD38− leukemia initiating stem cells." (PMID 35892900, 2022). "Also, the integrin alpha 6 gene (ITGA6, encoding CD49f), shown in several studies to be upregulated in HSC, playing an important role in HSC homing to the BM niche, and associating with poor therapy response in ALL, was among the top 5 upregulated genes in the CD34‐positive leukemias." (PMID 35271751, 2022). "Interestingly, though the proportions of sGRP78+ cells coexpressing CD34, CD38, CD10 or CXCR4 were significantly higher in High-risk leukemia population, these samples showed the presence of a subgroup of double positive cells rather than a general increase of the positivity to the analyzed markers." (PMID 35149705, 2022). "Hence, the association between CD34 and therapy response could potentially be biased, if a CD34‐positive immunophenotype was more informative, thus underestimating MRD in CD34‐negative leukemias." (PMID 35271751, 2022). "As demonstrated by acute leukemia cell lines and primary samples (of unknown age and leukemia type), the expression of the miR-24-2 cluster was found to be significantly decreased compared to CD34+ PBMCs from normal adult donors (86% of pre-B-ALL and 100% of T-ALL)." (PMID 36010971, 2022). "Moreover, leukemias could also only be engrafted in mice using primitive CD34+CD38- cells, whereas AML-CFU were most prevalent in the CD34+CD38+ cell population." (PMID 33807298, 2021). "In addition, the expression level of SUV39H1 in stem/progenitor-enriched CD34+ AML cells was significantly lower than in normal cord blood CD34+ cells, which may either be due to the age effect or the combinative effects of age and leukemia." (PMID 33037410, 2020). "Interestingly, increased lipid uptake points to the crucial role of microenvironment supporting cancer (stem) cell functions: tumor-activated adipocytes provide FAs to support leukemia CD34+ cells growth, survival and chemoresistance as well as omental metastasis from ovarian cancer." (PMID 30967773, 2019). "Besides its role in drug resistance, AXL is highly expressed in primary CD34+ leukemia stem cells and its expression is dependent on the breakpoint cluster region/abelson murine leukemia viral oncogene homolog 1 (BCR-ABL) protein level rather than its tyrosine kinase activity." (PMID 31694201, 2019). "Furthermore, high levels of CKS1B observed in haematopoietic stem and progenitor cells (CD34+) indicate that CKS1B may be a central factor of the stem cell program hijacked by MLL-FPs in MLLr leukaemia." (PMID 28939057, 2018). "Furthermore, we could show that the majority of leukemia-initiating cells, defined as being CD34+/CD38−, expressed PVR and PVRL2 or at least one of the immune checkpoint ligands (mean expression value 77%, range 51–93%, n = 10)." (PMID 29855615, 2018). "In addition to the anti-proliferation function, DS/Cu also had a marked effect on both induction of apoptosis and impairment of clonogenicity of leukemia stem-like cells, including primary CD34+ AML cells, with minimally toxicity towards normal counterparts obtained from healthy donors." (PMID 28518151, 2017).
leukemia (continued). "HSCs were isolated from mice using flow sorting of Lineage-, Sca-1+, c-Kit+, and CD34- cells from bone marrow prior to progression to leukemia; these cells are cancer stem cells which will eventually develop to myeloid proliferative disorder and leukemia in vivo or upon transplant." (PMID 28640831, 2017). "To examine whether some of the potentially deleterious variants accumulated before leukaemia development, we screened 20 variants found with a high penetrance in both T2‐ALL and AML‐M0 clones by NGS on CD34+ cells obtained from the patient's peripheral blood 5 years prior to T2‐ALL development." (PMID 27997762, 2017). "However, recent studies have found that more mature CD34+CD19+ leukemic blasts could initiate leukemia in ETV6-RUNX1- or TEL-AML1-positive B-ALL cases." (PMID 29034206, 2017). "Interestingly, the two types of normal myeloid cells, granulocytes and CD34+ progenitors, both showed a higher positive correlation between themselves than with a leukemia cell line K562 prompting us a more extensive analysis of H3K9me2 in human AML cell (below)." (PMID 28301528, 2017). "Furthermore, alantolactone was more toxic to CD34+CD38– cells than total primary leukemia cells." (PMID 27658462, 2016). "In addition, a novel approach based on the depletion of TCR α/β+ T cells and B cells in which fresh alloreactive NK cells are infused together with CD34+ cells supports the notion that also fresh NK cells may represent suitable effectors against leukemia." (PMID 27563819, 2016). "The resulting human leukemia may arise through genetic selection and we previously showed that human T-ALL development in immune-deficient mice is significantly enhanced upon CD7+/CD34+ leukemic cell transplantations." (PMID 27191650, 2016). "While the mechanism of Bcl-2 expression in CSC chemo/drug resistance is still unclear, and it might be due to chromosomal translocation or another pathway, it was demonstrated that leukaemia CD34+ cells expressed Bcl-2 and Bcl-X, and Bcl-2 was highly expressed in breast CD44+/CD24−/low CSCs." (PMID 27825361, 2016). "In addition to drug-screening capabilities, the value of molecular-sensitive SC-QDP measurements was illustrated in clinical samples by identification of CD34+ cells that are phosphoinsensitive to the kinase inhibitor, dasatinib, the standard KI for many leukemia patients with CML." (PMID 27320899, 2016). "Indeed, media conditioned by blast crisis leukemia Lin-CD34+ cells increased the ability of HS-5 cells to both penetrate through matrigel in a transwell assay and to degrade fluorescent gelatin compared to media conditioned by Lin-CD34+ cells from chronic phase or a healthy donor." (PMID 27802179, 2016). "Additionally, we are using this system to generate MLL translocations in CD34+ cells freshly isolated from umbilical cord blood followed by transplantation into immunocompromised (NSG) mice in order to develop a novel mouse model of MLL-rearranged leukemia." (PMID 26351841, 2015). "Thus, treatment of AML cells with CD82 mAb might enhance mobilization of CD34+ leukemia cells into the PB, although this was a transient effect." (PMID 26139471, 2015). "Specifically, microarray data of an established normal body atlas (n = 353) normal CD34+ HSCs (n = 35), macrophages (n = 45), monocytes (n = 26), B cells (n = 24), and T cells (n = 20) were compared with those for four major lymphoma and leukemia entities (n = 819)." (PMID 24913448, 2014). "Also in CD34 positive AML in the absence of CD34+CD38- cells, but with neoplastic CD34+CD38+ and CD34- populations present, the latter two populations may take over the leukemia initiating ability." (PMID 25244440, 2014). "Indeed, recent work has shown that CK2 inhibition dampens down the PI3K/AKT pathway with a reduction of the activity of downstream effectors such as Bcl-xl and NF-κB and cooperates with PI3K inhibitors in inducing cell death of CD34+ CD38- AML leukemia stem cells." (PMID 24283803, 2013).
leukemia (continued). "Importantly, As2O3/PI-103 combined treatment led to a loss of the potential of LICs (CD34+/CD38−) to regenerate non-APL leukemia in NOD/SCID mice." (PMID 22564882, 2012). "Thus they concluded that CD34+CD38- subpopulations were the initiating cells of leukemia." (PMID 21542915, 2011). "Taken together, these data confirm that overall alternative splicing of the c-myb gene was significantly elevated in leukemia samples compared to normal CD34+ cells, suggesting that alternative splicing of c-myb could provide a novel biomarker linked to prognosis or patient outcome." (PMID 21853052, 2011). "Thus far, differential expression of DOCK4 and SPARCL1 had never been associated to CD133+/CD34+ cell expansion or leukemias." (PMID 17559657, 2007). "In this work, we employed a Markov chain mathematical model to quantify the rates of cell state transitions between CD34+/CD38−, CD34+/CD38+, CD34−/CD38+, and CD34−/CD38− leukemia subpopulations in patients with B-ALL." (PMID 41295979, 2026). "Flow cytometry analysis showed reduced surface expression of c-Kit and CD34, markers of leukemic stemness, and similar differentiation effects were observed in KAT6A-TIF2 and KAT6A-NCOA3 leukemia cells, underscoring the broad impact of CBP/P300 inhibition." (PMID 40830799, 2025). "It is known that CD34- and CD117-positive leukemia compartments contain normal progenitors and leukemia-initiating and propagating cells." (PMID 40429651, 2025). "In contrast, we observed a peak over the +65kb CRE and over the HHEX proximal promoter/intron one enhancer in primary human HSPC cells (CD34+), primary human ETP-ALLs (n = 3), and, in LOUCY (ETP-ALL) and K562 human leukemia cell line models." (PMID 39880094, 2025). "The presence of CD34, cytoplasmic CD3, and partial myeloid markers (CD117, MPO) was crucial in classifying this leukemia as T/Myeloid MPAL." (PMID 40605863, 2025). "Previous reports demonstrated the presence of MLP-like progenitors in CD34+ cells derived from AML patients at diagnosis and the ability of these cells to induce leukemia." (PMID 40362463, 2025). "PTL was found to effectively trigger apoptosis in bulk B- and T-ALL cells in the xenograft model, though some leukemia-initiating cells subpopulations (CD34+/CD19−, CD34+/CD7−, and CD34−) showed greater resistance." (PMID 40303928, 2025). "In this work, we have used computational machine learning models to identify leukemia subtypes, i.e., Bone Marrow CD34, AML, PB, PBSC CD34." (PMID 40378164, 2025). "In leukemia, miR-203 expression is diminished in CD34 + AML cells, directly targeting survivin and Bmi-1 to impede the self-renewal ability of leukemia stem cells." (PMID 40710326, 2025). "have reported that a higher rate of apoptosis in the CD34+/CD117+ myeloid compartment is an independent favorable prognostic factor for both, OS and transformation to leukemia." (PMID 39544295, 2024). "Murine and human T-ALL cells expressing CD34 and high levels of MYC have been shown to possess leukemia-initiating cell (LIC) potential." (PMID 38352301, 2024). "To understand the regulatory underpinnings of their lineage ambiguity, we comprehensively profiled the epigenetic and transcriptional landscape of CIMP leukemias, as well as that of T-ALL, AML, and CD34+ cells from healthy donors." (PMID 38972954, 2024). "By using cell surface markers, CD34 and CD38, which identified progenitor and pluripotent stem cells in bone marrow, AML-initiating cells that produced leukemia when transplanted in immunodeficient mice were observed to be CD34+CD38− cells." (PMID 39335624, 2024). "Nonetheless, these observations collectively suggest leukemia-specific proximity of CD74+CD68+ cells and CD34+ primitive cells, and a potential support role for RECs in AML regeneration that forms the basis of functional testing." (PMID 38582086, 2024).
leukemia (continued). "Next, we assessed the frequency of L-GMPs (Lin− Sca1− c-Kit+ CD34+ FcgR+) by flow cytometry, which have been described as the functionally relevant LSC population in MA9 driven leukemia." (PMID 38049829, 2023). "To establish a connection between our model-based analysis and the clinic, we also analyzed patient samples with MLLr leukemia using RT-qPCR, which revealed significant NOTCH1 overexpression compared with huCB-derived CD34+ cells." (PMID 37833915, 2023). "As leukemia-initiating AML cells can reside in the CD34+CD38+ compartment, treatment with the recombinant antibody daratumumab against CD38 inhibits mitochondrial transfer to AML blasts, inhibiting the leukemia growth." (PMID 38169927, 2023). "Leukemia stem cells (LSCs), a subpopulation of leukemic cells are characterized with CD34+/CD34+CD38- phenotypes that can self-renew and initiate leukemia." (PMID 37644011, 2023). "We focused on patients with CD34+ leukemia (AMLCD34+), the most common immunophenotype in AML, to facilitate the enrichment of less differentiated VLBs (i.e., CD34+) and improve homogeneity of the examined cells." (PMID 36927800, 2023). "The expression of CD34 and CD45 was assessed using flow cytometry to further pinpoint leukemia infiltration in vivo." (PMID 37392305, 2023). "Compared to CD34, which is expressed in leukemic cells of various origins, CD117 is a specific marker for leukemia of myeloid origin." (PMID 37754227, 2023). "In human acute myeloid leukemia, the existence of leukemia stem cells (LSC) is well-established and shown to be phenotypically restricted to CD34+CD38-cells." (PMID 37173970, 2023). "Linear programming model classifies and predicts the subtypes of leukemia Bone_Marrow_CD34, Bone Marrow, AML, PB, and PBSC CD34." (PMID 37812613, 2023). "Here, we demonstrate that combined inhibition of Bcl-2 by venetoclax and activation of PPARα by chiglitazar has synergistic anti-leukemia activity against LSC-like cell lines (KG-1α and Kasumi-1) and CD34+ primary AML cells while sparing normal cells in vitro." (PMID 37644011, 2023). "Based on the comparison of the expression of SNORD42 in leukemia cells, CD34+ progenitor cells, monocytes, and granulocytes in patients with primary AML, the expression of SNORD42 in leukemia cells was significantly enhanced." (PMID 37492704, 2023). "In AML-mesenchymal stromal cells (MSCs)-CD34+ cells co-cultured system, this a novel COX2/NR4A1/CTNNB1 axis increased leukaemia-reactive T-effector cells and rescued cellular metabolism and anti-leukaemia immunity." (PMID 36052242, 2022). "The rare subset that marked the CD34+CD38- population was the same as that of normal hematopoietic stem cells (HSCs), and was defined as leukemia stem cells (LSCs)." (PMID 35865470, 2022). "Due to the key role that β-catenin has in the maintenance of AML self-renewal and survival, we examined the effects of NUC-7738 on the colony forming capability of leukemia cells, in addition to measuring the percentage of LSC-like cells (CD34+CD38-CD123+)." (PMID 36520954, 2022). "We therefore reconstituted SGM3 mice with human cord blood CD34+ cells and infused humanized mice (HuSGM3) with NALM-6 leukemia cells." (PMID 35503659, 2022). "Once established, the leukaemia cells secrete high levels of SCF to attract and outcompete native HSPC niches for engraftment of normal CD34+ cells." (PMID 36614005, 2022). "A recent study tracking the leukemia cells of AML patients before and after chemotherapy found that CD34+CD38- LSCs and AML blasts were equally eliminated, and LSCs no longer remained quiescent after chemotherapy." (PMID 35865470, 2022). "CD34, CD99, and CD43 are also sensitive markers for the diagnosis of lymphoblastic lymphoma/leukemia." (PMID 35372059, 2022). "In hematopoietic malignancies, HCSCs (also known as leukemia stem cells, LSCs) have been identified in acute myeloid leukemia (AML) in the 1990s, with specific markers such as CD34+/CD38−." (PMID 35659296, 2022).
leukemia (continued). "Both c-KIT and CD34 are hematopoietic stem/progenitor markers; particularly, c-KIT is also the leukemia stem cell marker." (PMID 36232694, 2022). "A robust engraftment of primitive CD34+CD38- leukemic progenitors, also known as NOD/SCID leukemia-initiating cells (NOD/SL-IC) or leukemic stem cells (LSC), was observed in NOD/SCID mice." (PMID 35756660, 2022). "Despite this apparent increase in mitochondrial content, JH+OXPHOS remained elevated above quiescent CD34 +only in PBMC, as OXPHOS kinetics were completely unaltered comparing CD34+GFs or primary leukemia to quiescent CD34+." (PMID 34132194, 2021). "Several studies have pinpointed TIM-3 as a promising candidate for targeting AML leukemia stem cells, as its higher expression levels were observed on LSCs (defined as CD45+CD34+CD38- or Lin-CD34+CD38-CD90-) than on normal HSCs." (PMID 33801964, 2021). "It is known that CD34-positive, CD117-positive, and CD133-positive leukemia compartments contain normal progenitors and leukemia initiating and propagating cells." (PMID 34073205, 2021). "The CK2 and BCL-XL expression were noted to be significantly and uniformly lower in CD34+ from PB and UCB compared to the leukemia cells." (PMID 33807974, 2021). "Another group built a six-gene leukemia stem cell (LSC) score with the incorporation of DNMT3B, GPR56, CD34, SOCS2, SPINK2, and KIAA0125 expressions for pediatric AML." (PMID 33225420, 2021). "Next, western blotting analysis was revealed that PTL decreased the levels of caspase 3 and increased the levels of activated caspase 3 and PARP in differentiated leukemia cells (CD34-CD38+) and LSCK562/ADM (CD34+CD38-)." (PMID 34405014, 2021). "Nuclear p63 and p40 staining were evident in most cases, and CD34 positivity is helpful for distinguishing between NMC cases and leukemia." (PMID 32149149, 2020). "The leukaemia PDX models were characterized by a definite expression pattern of surface markers determined by FC: CD45, CD34 and CD38 were expressed in a model specific percentage on the tumour cells." (PMID 32466316, 2020). "Pabst and colleagues furthermore observed various level of LSC activity in PDX assays for cells expressing different levels of CD34 and GPR56, with the double positive population showing the highest in vivo leukemia-initiating capacity." (PMID 33322769, 2020). "However, while we originally screened six leukemia cell lines for CD34 expression, Kasumi-1 was the only cell line that we ultimately decided to use as a model for chemosensitivity evaluation, since the differentiation stage of each subpopulation could be separately examined during culture." (PMID 32433559, 2020). "Ro affected viability of CD34+ cord blood cells at an EC50 of ∼22 μM, 2.6-fold higher concentration than the human leukemia cell lines." (PMID 31217428, 2019). "By using western blotting analysis, the BRD9 protein levels in CD34+ cell and some cancer cell lines (HL60, K562 and U937) were compared, another research represented that this protein was also elevated in leukemia and lymphoma." (PMID 31504061, 2019). "Correlations between mRNA and protein expressions of CD34 and CD56 genes have been studied and reported previously in two independent studies using leukemia samples." (PMID 31171000, 2019). "Further, CD34+CD38− cells in KG-1, KG-1a, TF-1, and primary leukemia cells were more sensitive to HHT and ATO." (PMID 31307525, 2019). "Functional analyses conducted in mice and human CD34 normal and leukemic cells have demonstrated the role of ERG in the induction of early myeloid progenitors in leukemia stem cell through the activation of RAS pathway and Pim1." (PMID 30303964, 2018). "This 123b-33bcCAR was designed to deplete AML cells by targeting both bulky disease and the CD34+CD38−CD123+ leukemic population to eliminate active disease and prevent leukemia relapses." (PMID 29515236, 2018).